ZFAND4 (zinc finger AN1-type containing 4)
Synonyms: ANUBL1; FLJ40185
Tractability: PROTAC: ubiquitination databases record sites on it.
Gene: Protein-coding gene on chromosome 10 (45,613,375 to 45,673,047, reverse strand). Ensembl gene ENSG00000172671.
Subcellular location (Human Protein Atlas): Golgi apparatus
Gene Ontology:
Molecular function: zinc ion binding
Genetic constraint (gnomAD): Loss-of-function variants: 39 observed, 60.44 expected, observed/expected ratio (o/e) 0.65, 90% interval 0.5 to 0.84. The upper end of that interval is the gene's LOEUF score, 0.84, which puts it in group 3 of 6, group 1 being the genes least tolerant of losing a copy. Missense variants: 901 observed, 871.23 expected, observed/expected ratio (o/e) 1.03, 90% interval 0.98 to 1.09. Synonymous variants: 288 observed, 314.27 expected, observed/expected ratio (o/e) 0.92, 90% interval 0.83 to 1.01.
Homologues: Orthologues: chimpanzee ZFAND4 (98% identical), macaque ZFAND4 (93% identical), pig ZFAND4 (78% identical), mouse Zfand4 (72% identical), rat Zfand4 (68% identical), rabbit ZFAND4 (63% identical), zebrafish zfand4 (43% identical). Paralogues in human: ANKUB1 (9% identical), UBC (8% identical), RPS27A (7% identical), UBA52 (6% identical), UBL4A (6% identical), UBL4B (6% identical), ISG15 (4% identical), NEDD8 (4% identical), UBD (3% identical), UBB (3% identical).
Diseases named in the same sentence as ZFAND4 in open-access papers:
ZFAND4 is named in the same sentence as 7 diseases in open-access papers, as found by Europe PMC text mining. Sharing a sentence is not in itself a finding about the gene and the disease. The quoted sentences say what the papers report.
gastric cancer (3 papers, 2018 to 2021). A primary or metastatic malignant neoplasm involving the stomach. "Although higher ZFAND4 expression, regulated by miR-182, strongly correlated with clinical stage progression in gastric cancer, little information is available about the functional roles of ZFAND4 in malignancies." (PMID 30115834, 2018). "ZFAND4, also known as ANUBL1, is a zinc-ion-binding protein that was found to be upregulated in gastric cancer." (PMID 33545363, 2021).
lymph node metastasis (2 papers, 2018). "In marked contrast, our results only proved a marginal (if any) relationship between ZFAND4 expression and the presence of lymph node metastasis." (PMID 30544692, 2018). "The cytoplasmic expression of ZFAND4 was detected in 21% (45/214) of OSCC cases, and there appears to be a link between ZFAND4 expression and lymph node metastasis, lymphatic invasion, vascular infiltration, and poorer outcome." (PMID 30115834, 2018).
oral squamous cell carcinoma (2 papers, 2018 to 2021). "Zinc finger AN1-type containing 4 (ZFAND4) has emerged as a promising prognostic marker and predictor of metastasis for patients with oral squamous cell carcinoma (OSCC)." (PMID 30544692, 2018).
Sepsis (1 paper, 2023). Sepsis is defined as life-threatening organ dysfunction caused by a dysregulated host response to infection. "In the present study, mutations in ENTPD1, ZFAND4, DNAH11 and LAMA2 increased the risk of comorbid sepsis in severely burned patients." (PMID 36659877, 2023). "Through genomic analysis, we identified seven important susceptibility genes (DNAH11, LAMA2, ABCA2, ZFAND4, CEP290, MUC20 and ENTPD1) in patients with severe burn injuries complicated with sepsis." (PMID 36659877, 2023). "At the genetic level, seven susceptibility genes for sepsis in severe burn patients were found: DNAH11, LAMA2, ABCA2, ZFAND4, CEP290, MUC20 and ENTPD1." (PMID 36659877, 2023). "The DNAH11, ZFAND4, LAMA2 and ENTPD1 genes have been shown to have protective effects against sepsis." (PMID 36659877, 2023).
cancer (1 paper, 2018). A tumor composed of atypical neoplastic, often pleomorphic cells that invade other tissues. "When the maximum Allred score was used, 31 patients (40.7%) with high ZFAND4 expression in the undifferentiated cells, and 20 patients (36.3%) with high ZFAND4 expression in the differentiated cells died due to the index cancer." (PMID 30544692, 2018). "Over a median follow-up period of 61 months, 27 patients (42.1%) harboring high ZFAND4 expression in undifferentiated cells calculated by using the mean Allred score died due to the index cancer, and 15 patients (41.6%) with high ZFAND4 expression in the differentiated cells." (PMID 30544692, 2018).
infection (1 paper, 2025). The state of being infected such as from the introduction of a foreign agent such as serum, vaccine, antigenic substance or organism. "The Ml exhibits a coordinated response to infection, characterized by upregulated DNA repair and immune-regulatory proteins that maintain genomic stability and immune balance, while a slight reduction (ZFAND4) in protein stress defenses indicates mildly compromised protein homeostasis." (PMID 41333726, 2025).
tumor (1 paper, 2018). "Only a trend was observed between low ZFAND4 expression in differentiated cells and tumor-associated deaths." (PMID 30544692, 2018). "Taking this into consideration, the Allred score was determined in two different ways: Either considering the maximum value of ZFAND4 positivity or the mean value of the three tumor cores." (PMID 30544692, 2018). "Moreover, Allred scores were calculated using both maximum value and mean value of ZFAND4-positive cells for the three tissue cores selected from each tumor." (PMID 30544692, 2018). "Since ZFAND4 expression showed two distinct non-overlapping expression patterns depending on the differentiation areas of tumors, each with a clearly distinct clinical significance, evaluation of ZFAND4 expression in the whole tumor could therefore be misleading." (PMID 30544692, 2018). "High ZFAND4 expression in differentiated cells was significantly associated to well-differentiated (p = 0.04) and non-recurrent tumors (p = 0.04), whereas ZFAND4 expression in undifferentiated cells correlated with tumor location (p = 0.005)." (PMID 30544692, 2018). "Thus, positive ZFAND4 immunostaining was scored in the whole tumor as the diffuse staining in tumor islands, cords, or sheets, irrespective of the cell differentiation status and the grade of keratinization." (PMID 30544692, 2018).